TMEM184B (transmembrane protein 184B)
Description:
May activate the MAP kinase signaling pathway.
Synonyms: C22orf5; HS5O6A; DKFZP586A1024; FM08; SLC51C2; HSPC256
Tractability: Antibody: UniProt predicts a signal peptide or a membrane-spanning region. PROTAC: ubiquitination databases record sites on it.
Gene: Protein-coding gene on chromosome 22 (38,219,290 to 38,273,805, reverse strand). Ensembl gene ENSG00000198792.
Subcellular location: Membrane
Subcellular location (Human Protein Atlas): Golgi apparatus; Cytosol; Nucleoplasm
Gene Ontology:
Molecular function: transmembrane transporter activity
Biological process: transmembrane transport
Cellular component: membrane
Genetic constraint (gnomAD): Loss-of-function variants: 17 observed, 41.64 expected, observed/expected ratio (o/e) 0.41, 90% interval 0.28 to 0.61. The upper end of that interval is the gene's LOEUF score, 0.61, which puts it in group 2 of 6, group 1 being the genes least tolerant of losing a copy. Missense variants: 393 observed, 558.35 expected, observed/expected ratio (o/e) 0.7, 90% interval 0.65 to 0.76. Synonymous variants: 240 observed, 229.36 expected, observed/expected ratio (o/e) 1.05, 90% interval 0.94 to 1.16.
Homologues: Orthologues: chimpanzee TMEM184B (99% identical), pig TMEM184B (99% identical), guinea pig TMEM184B (98% identical), dog TMEM184B (98% identical), mouse Tmem184b (96% identical), rat Tmem184b (96% identical), rabbit TMEM184B (88% identical), tropical clawed frog tmem184b (86% identical), zebrafish tmem184ba (82% identical), zebrafish tmem184bb.1 (75% identical), zebrafish tmem184bb.2 (75% identical), Caenorhabditis elegans tmem-184 (56% identical). Paralogues in human: TMEM184A (62% identical), TMEM184C (32% identical), SLC51A (13% identical).
Diseases named in the same sentence as TMEM184B in open-access papers:
TMEM184B is named in the same sentence as 24 diseases in open-access papers, as found by Europe PMC text mining. Sharing a sentence is not in itself a finding about the gene and the disease. The quoted sentences say what the papers report.
melanoma (2 papers, 2017 to 2024). A malignant, usually aggressive tumor composed of atypical, neoplastic melanocytes. "Indeed, all genes associated with nevus count or cutaneous nevi in cluster 6 (MTAP, TUBBP1, PLA2G6, ERVFRD.3, TMEM184B, BAIAP2L2) were only associated with melanoma." (PMID 38308491, 2024).
Alzheimer’s dementia (1 paper, 2023). "TMEM184B was predicted in human transcriptome analyses to be associated with deleterious gene expression that could drive the progression of Alzheimer’s dementia." (PMID 37730546, 2023).
Anxiety (1 paper, 2023). Intense feelings of nervousness, tension, or panic often arise in response to interpersonal stresses. "Taken together, our data suggest that TMEM184B is required for proper synaptic gene expression and anxiety-related behavior and is more likely to be linked to neurodevelopmental disorders than to dementia." (PMID 37730546, 2023). "While young adult Tmem184b-mutant mice do not have impaired memory, we uncovered an unexpected effect of TMEM184B loss on anxiety behavior." (PMID 37730546, 2023). "While we did not complete an exhaustive behavioral analysis, we found that TMEM184B disruption causes reduced anxiety in females in the elevated plus maze paradigm." (PMID 37730546, 2023). "Surprisingly, we identified a decreased anxiety overall in Tmem184b-mutant mice when compared to wild types." (PMID 37730546, 2023). "This indicates that TMEM184B is required for appropriate anxiety levels in females in the elevated plus maze assay." (PMID 37730546, 2023). "To understand how TMEM184B disruption may impact behaviors, we evaluated memory using the novel object recognition test and anxiety using the elevated plus maze." (PMID 37730546, 2023). "Therefore we suspect that it is an overall network change, rather than any individual gene, that is contributing to synaptic alterations leading to our observation of decreased anxiety in Tmem184b-mutant mice, especially in females." (PMID 37730546, 2023). "Thus it is plausible that in the absence of TMEM184B, Wnt signaling pathways show reduced activation, leading to a decrease in adult neurogenesis, a disruption of hippocampal function, and an altered anxiety response; these links must be formally tested in future work." (PMID 37730546, 2023).
atopic dermatitis (1 paper, 2023). "TMEM184B loss in DRG neurons causes disruption of sensation of interleukin-31, a key cytokine involved in atopic dermatitis (eczema) that is detected exclusively by SST + neurons." (PMID 37730546, 2023).
autism (1 paper, 2024). Persistent deficits in social interaction and communication and interaction as well as a markedly restricted repertoire of activity and interest as well as repetitive patterns of behavior. "Four Qualifying variants in B1 genes (with published indirect association with autism) were identified in four subjects, in the following genes: BRPF3, GTF2A1, POGLUT3, and TMEM184B, including a de novo loss-of-function variant in POGLUT3." (PMID 38256266, 2024).
coronary artery disease (1 paper, 2022). "Similarly, Ji et al26 found that TMEM184B might crucially influence the occurrence and development of coronary artery disease by participating in the OIP5‐AS1‐miR‐25‐3p‐TMEM184B ceRNA regulatory network." (PMID 36254814, 2022).
dementia (1 paper, 2023). Loss of intellectual abilities interfering with an individual's social and occupational functions. "Instead, we hypothesize that compromising TMEM184B function, in the presence of other susceptibility loci, may increase the likelihood of developing dementia." (PMID 37730546, 2023). "Our work places TMEM184B into a gene regulatory network that could impact synaptic connectivity and, rather than cause dementias, may instead be linked to neurodevelopmental disease." (PMID 37730546, 2023).
Huntington disease (1 paper, 2023). Huntington disease (HD) is a rare neurodegenerative disorder of the central nervous system characterized by unwanted choreatic movements, behavioral and psychiatric disturbances and dementia. "Furthermore, it suggested that pathways dysregulated in Tmem184b-mutants are enriched for those contributing to neurodegenerative diseases including Parkinson’s disease, ALS, Spinocerebellar ataxia, and Huntington’s Disease." (PMID 37730546, 2023).
hypopharyngeal squamous cell carcinoma (1 paper, 2022). "Several members of the transmembrane protein family are associated with the biological processes of human malignancies; however, the expression pattern and biological function of one family member, TMEM184B, in hypopharyngeal squamous cell carcinoma (HPSCC) are not fully understood." (PMID 36254814, 2022).
retinal degeneration (1 paper, 2025). Degeneration of the retina. "Overall, our data demonstrate a novel regulating mechanism of TMEM184B in retinal degeneration, providing a novel potential target for RD therapy development." (PMID 39375958, 2025). "Progressive retinal degeneration was observed in Tmem184b KO mice." (PMID 39375958, 2025). "Additionally, the down‐regulated genes in the response to hypoxia pathway may indicate a possible mechanism of action to Tmem184b KO‐induced retina degeneration." (PMID 39375958, 2025).
cancer (4 papers, 2019 to 2024). A tumor composed of atypical neoplastic, often pleomorphic cells that invade other tissues. "The researchers concentrated specifically on the category “Regulation of actin cytoskeletal pathway” based on the characteristics of cancer cells after silencing TMEM184B or inducing miR-26a/b." (PMID 38792263, 2024). "Accordingly, the results showed that miR-26a/b downregulation promoted cancer cell migration and invasion by upregulating TMEM184B expression and activating actin cytoskeleton pathways." (PMID 38792263, 2024). "Through the control of TMEM184B, the loss of tumour-suppressive miRNA-26a/b in OSCC promotes cancer cell motility and invasion." (PMID 38792263, 2024). "The roles of TMEM184B in the biological processes of cancer are also gaining attention." (PMID 36254814, 2022). "MiR-26a-5p inhibits migration and invasion of cancer cells by targeting the TMEM184B gene." (PMID 33396321, 2020). "Consequently, the tumour-suppressive miR-26a/b-TMEM184B axis may be used as a target for cancer metastasis therapy." (PMID 38792263, 2024). "Furthermore, we searched the public database (The Cancer Genome Atlas) and literatures and found that TMEM184B is one of novel TMEM proteins whose role and function have not been fully elucidated in human cancers, including HPSCC." (PMID 36254814, 2022).
nervous system disorder (2 papers, 2023 to 2025). A non-neoplastic or neoplastic disorder that affects the brain, spinal cord, or peripheral nerves. "Taken together, our analysis of transcriptomic changes in Tmem184b-mutant hippocampus predicts significant dysregulation of neuronal function that may be linked to neurological disease." (PMID 37730546, 2023).
neurodevelopmental disorder (2 papers, 2023 to 2025). A behavioral and cognitive disorder with onset during the developmental period that involves impaired or aberrant development of intellectual, motor, or social functions. "Transmembrane protein 184B (TMEM184B) is a conserved seven-pass transmembrane protein that is essential for synaptic function, and its sequence disruption is associated with neurodevelopmental disorders." (PMID 40586707, 2025).
tumour (2 papers, 2022 to 2024). "Compared with normal tissues, a similar significant change in TMEM184B expression in cancerous tissues was observed in HPSCC tumours in both the TCGA and GSE58911 databases." (PMID 36254814, 2022). "Furthermore, in vitro assays on cell proliferation, invasion, migration and in vivo experiments on tumour growth and apoptosis of TMEM184B in HPSCC were performed." (PMID 36254814, 2022).
cardiovascular diseases (1 paper, 2021). "The role of TMEM184B in cardiovascular diseases has never been reported, which is worth of further research." (PMID 34631806, 2021).
TMEM184B also shares sentences with these, for which no sentence is quoted: breast carcinoma (3 papers); nevus (2); eczema (1); glioma (1); neurodegenerative disease (1); Parkinson disease (1); retina inflammation (1); Retinal dystrophy (1); Spinocerebellar ataxia (1).